Y_RNA (Y RNA )
Gene: Miscellaneous RNA gene on chromosome 2 (172,558,151 to 172,558,252, reverse strand). Ensembl gene ENSG00000199866.
Homologues: Orthologues: chimpanzee Y_RNA (100% identical), guinea pig Y_RNA (94% identical). Paralogues in human: Y_RNA (93% identical), RNY3 (92% identical), Y_RNA (92% identical), RNY3P1 (91% identical), Y_RNA (91% identical), Y_RNA (90% identical), Y_RNA (89% identical), RNY3P4 (88% identical), Y_RNA (88% identical), RNY3P14 (87% identical), Y_RNA (87% identical), RNY3P11 (86% identical), and 98 more.